CAV1 (caveolin 1)
Diseases named in the same sentence as CAV1 in open-access papers (continued):
Sharing a sentence is not in itself a finding about the gene and the disease.
pulmonary hypertension (continued). "Cav-1 levels are also altered in renal failure and pulmonary hypertension." (PMID 24251870, 2013). "Moreover, in addition to Cav-1, Cav-2 was also reduced in rats with moncrotaline-induced pulmonary hypertension." (PMID 26605130, 2012). "Furthermore, these authors also observed decreased expression of Cav-1 in lungs of patients with severe pulmonary hypertension." (PMID 26605130, 2012). "Moreover, marked reduction of endothelial Cav-1 has been reported in a number of clinical and experimental forms of pulmonary hypertension." (PMID 26605130, 2012). "For instance, physiological or higher expression levels of caveolin-1 in endothelium might be beneficial in such diseases as pulmonary hypertension, cardiac hypertrophy, or ischemic injury." (PMID 26605130, 2012). "Several independent studies have demonstrated pulmonary arterial hypertension in Cav1 KO mice." (PMID 26605130, 2012). "Similarly, it has been reported that simvastatin upregulates caveolin-1 expression in human smooth muscle cells and macrophages and normalizes the vascular cell phenotype in severe pulmonary hypertension." (PMID 19816600, 2009). "Furthermore, Cavin-1 knockdown is resistant to CAV1-induced pulmonary hypertension in vivo." (PMID 38182755, 2024). "Moreover, knockdown of cavin-1 renders it resilient to CAV1-driven pulmonary hypertension in vivo." (PMID 39507419, 2024). "Caveolin-1 functioning may be sufficiently studied in pulmonary arterial hypertension." (PMID 37273690, 2023). "However, a study on the lungs of rats exposed to hypobaric hypoxia found that PTEN expression was decreased but that the membrane localization of its regulator caveolin-1 (cav-1) was unchanged, which could contribute to hypoxia-induced pulmonary hypertension." (PMID 34434114, 2021). "Moreover, Cav-1-dependent signaling is impaired in pulmonary hypertension." (PMID 34490843, 2021). "Hence, chronic hyperactivation of eNOS may be a secondary effect of Cav1 KO that produces pulmonary precapillary structural abnormalities that lead to pulmonary hypertension." (PMID 32940661, 2020). "However, the role of caveolin-1 in pulmonary hypertension varies in different vascular cells." (PMID 32257548, 2020). "Thus, development of therapeutic approaches involving endothelium-specific delivery of Cav-1 mimicking peptides or gene therapy restoring Cav-1 expression in endothelium of patients with pulmonary hypertension could be of clinical significance." (PMID 26605130, 2012). "Based on this data, the authors suggested that a perturbation of NO signaling, together with enhanced superoxide production originating from NO synthases, could play a pivotal role in the pathogenesis of the pulmonary arterial hypertension seen in Cav-1 KO mice." (PMID 26605130, 2012). "Caveolin-1 (CAV1) is a negative regulator of NOX2 in the normal pulmonary circulation and genetic ablation of CAV1 increases NOX2 expression and activity and worsens pulmonary hypertension." (PMID 34068984, 2021). "BMPR: bone morphogenic protein receptor type II; CAV1: caveolin-1; ENG: endoglin; HIV: human immunodeficiency virus; PAH: pulmonary arterial hypertension." (PMID 25165714, 2014). "In another rat model of severe pulmonary hypertension, induced by a single subcutaneous injection of the VEGFR inhibitor SU5416 and subsequent 3-week exposure to chronic hypoxia, Cav1 expression was selectively reduced in the arterial lesions." (PMID 26605130, 2012). "Remarkably, as determined in a rat model of chemically-induced pulmonary hypertension, similar increases in tyrosine phosphorylated STAT3, and the expression levels of cyclin D1 and D3 were observed in whole lung homogenates from Cav-1 and Cav- 2 KO mice." (PMID 26605130, 2012). "In addition, among the DEGs involved in the hypoxic pathway in IPAH, the expression of CAV1, JUN, and PDGFB, which promote the progression of pulmonary hypertension, were all increased." (PMID 38586587, 2024).
pulmonary hypertension (continued). "Cavin-1 and BMPR2 competitively interact with the Caveolin-1 scaffolding domain that modulate BMP/Smad signal transduction in pulmonary artery endothelial cells and these interactions are involved in the development of pulmonary hypertension." (PMID 38182755, 2024). "In this article, global Cav1 KO mice exhibited increased pulmonary hypertension; however, this pathology was absent in double eNOS and Cav1 KO mice." (PMID 32940661, 2020). "In pulmonary hypertension, Cav-1 is a negative regulator of ROS derived from NO since lack of Cav-1 expression in pulmonary hypertension increases NOX activity and enhances ROS production." (PMID 33519523, 2020). "It is worth to note that downregulated pulmonary CAV-1 expression subjected to myocardial infarction may lead to STAT3/Cyclin pathway activation, pulmonary hypertension, and lung structural remodeling development." (PMID 32565767, 2020). "In this study, we analyzed 7 PAH-causing genes including BMPR2, ACVRL1, ENG, SMAD9, CAV1, KCNK3, and CBLN2 in 49 CTEPH patients and 17 patients recovered from pulmonary embolism (PE) but without pulmonary hypertension(PH)." (PMID 26820968, 2016). "Taken together, our results demonstrated that reduced serum Cav1 level may be a potential biomarker in IPAH diagnosis and could be used for differential diagnosis of pulmonary artery hypertension patients between idiopathic pulmonary hypertension and COPD." (PMID 26539466, 2015). "Interestingly, in addition to rats with chemically-induced pulmonary hypertension, a similar increase in tyrosine phosphorylated STAT3, and the expression levels of cyclin D1 and D3 were observed in whole lung homogenates from Cav-1 KO mice." (PMID 26605130, 2012). "For example, in one study, treating Cav-1 KO mice with the NOS inhibitor l-NAME in the first two months of life, resulted in a complete reversal of pathological pulmonary changes, heart hypertrophy and pulmonary arterial hypertension." (PMID 26605130, 2012). "However, unlike in Cav-1 KO mice, the possibility that Cav-2 KO mice have pulmonary hypertension was not examined." (PMID 26605130, 2012). "Thus therapeutic approaches restoring Cav-1 expression in endothelium, using cell-permeable CSD peptide, could potentially be useful in treatment of pulmonary hypertension." (PMID 26605130, 2012). "Since eNOSis an important target of Cav-1, it is not surprising that numerous studies explored the possibility that changes in eNOS activity and function could be responsible for the pulmonary hypertension seen in Cav-1 KO mice." (PMID 26605130, 2012). "Similarly, in pulmonary arterial hypertension (PAH), antibody-mediated CD47 blockade lowers right ventricular systolic pressure and attenuates hypertrophy, effects attributed partly to suppression of TSP1 and restoration of caveolin-1 levels in pulmonary tissue." (PMID 41303525, 2025).
pulmonary fibrosis (62 papers, 2010 to 2025). Chronic progressive interstitial lung disorder characterized by the replacement of the lung tissue by connective tissue, leading to progressive dyspnea, respiratory failure, or right heart failure. "Another analogous study identified through high-throughput sequencing revealed that miR-552-3p and its predicted target gene Caveolin 1 (CAV1) are associated with pulmonary fibrosis." (PMID 39479511, 2024). "At the same time, it can reverse bleomycin-induced pulmonary fibrosis and attenuate lethality, weight loss, and the expression of pulmonary senescence markers by promoting FasL receptor and caveolin-1 expression and inhibiting AKT activation." (PMID 35672815, 2022). "These included Cav1, which is required for normal lung development and Dsp, variants of which are associated with idiopathic pulmonary fibrosis." (PMID 29630593, 2018). "Considering an increase in caveolin-1 has been linked to pulmonary fibrosis 36, studies in this model addressing the role of caveolin-1 in the cause and reduction of pulmonary fibrosis in this model is warranted." (PMID 26304628, 2015). "In this study, we have examined cellular mechanisms involved in lung fibrosis that are affected when the deficiency of caveolin-1 in fibrotic lung tissue is reversed using specific subdomains of the CSD peptide and mutated versions of the CSD peptide." (PMID 24011378, 2013). "This short list included CAV1, a structural component of caveolae, previously associated with lung fibrosis." (PMID 23459460, 2013). "In addition, Caveolin-1 has been implicated in lung fibrosis and remodeling, with earlier studies showing its role as a regulator of tissue injury and repair, and more recent work confirming its critical functions in maintaining pulmonary homeostasis." (PMID 41010338, 2025). "Notably, previous studies have linked Caveolin-1 to lung fibrosis and impaired repair in chronic lung diseases, emphasizing its dual role in both development and disease." (PMID 41010338, 2025). "Furthermore, they investigated the therapeutic effects of Cav-1 in rat lungs using bleomycin, an antineoplastic antibiotic that causes pulmonary fibrosis as a major side effect." (PMID 28970796, 2017). "Context: Previous studies have reported that caveolin-1 (Cav-1) is associated with lung fibrosis." (PMID 27937011, 2017). "Expression of Cav-1 is implicated in the pathogenesis of pulmonary fibrosis." (PMID 22040717, 2011). "Cav‐1 is abundant in pericyte membranes, where it contributes to the regulation of vascular tone and pulmonary fibrosis." (PMID 40778471, 2025). "Cav‐1 regulates collagen expression in cultured lung fibroblasts both in vitro and in vivo, and during pulmonary fibrosis." (PMID 40778471, 2025). "It thus remains to be seen if the promising outcomes of Cav-1 gene therapy for idiopathic pulmonary fibrosis can be replicated in humans as well." (PMID 36760400, 2023). "In subsequent organizational progression with pulmonary fibrosis, caveolin-1 appears to be protective, where it exerts pro-apoptotic and anti-proliferative effects on mesenchymal cells, including lung fibroblasts and myofibroblasts." (PMID 36831221, 2023). "Among candidates for more effective treatment of IPF and potentially other forms of pulmonary fibrosis, targeting caveolin-1 has emerged as a promising interventional approach." (PMID 36831221, 2023).
pulmonary fibrosis (continued). "In multiple mouse models of experimentally induced lung fibrosis, caveolin-1 scaffolding domain peptide (CSP) has been shown to alleviate PF." (PMID 35328736, 2022). "Caveolin-1 scaffolding domain peptide (CSP) has been found to mitigate pulmonary fibrosis in several animal models." (PMID 35328736, 2022). "CXCL10 was used to alleviate fibrosis disease, such as bleomycin-induced pulmonary bleomycin-induced pulmonary fibrosis, and p-Cav-1 was also reported to be key player in the process of fibrosis." (PMID 34790658, 2021). "Fibroblasts from idiopathic pulmonary fibrosis lungs exhibit low caveolin-1 levels accompanied by low membrane PTEN levels; the overexpression of caveolin-1 has been shown to restore PTEN expression." (PMID 34698188, 2021). "In our pulmonary fibrosis mice model, it was further demonstrated that the mRNA expression level of CAV1 in bleomycin-induced pulmonary fibrosis tissues was significantly lower compared to the normal control group." (PMID 35069688, 2021). "Except Cav1, emerging evidence showed that Cav2 was also involved in the regulation of pulmonary fibrosis." (PMID 32694556, 2020). "The overexpression of Cav1 reduced the infiltration of monocytes/macrophages in a mouse model of pulmonary fibrosis." (PMID 33015095, 2020). "Collectively, these results demonstrate that electroporation-mediated gene transfer of Cav-1 can protect against subsequent bleomycin-induced pulmonary fibrosis and abrogate pulmonary inflammatory response to bleomycin injury." (PMID 31873099, 2019). "Gene transfer of a plasmid expressing Cav-1 using transthoracic electroporation reduced infiltration of neutrophils and monocytes/macrophages and protected from subsequent bleomycin-induced pulmonary fibrosis." (PMID 31873099, 2019). "In this study, we show that electroporation-mediated gene transfer of plasmids expressing Cav-1 can protect from bleomycin-induced pulmonary fibrosis through downregulation of inflammasome activity in the lung epithelium." (PMID 31873099, 2019). "Taken together, our data indicate that electroporation-mediated gene transfer of Cav-1 protects from bleomycin-induced pulmonary fibrosis through downregulating inflammasome activity in the lung epithelium." (PMID 31873099, 2019). "It has been reported that miR-199a-5p promotes the differentiation of fibroblasts into myofibroblasts by regulating caveolin-1, a key mediator of pulmonary fibrosis, to induce pulmonary fibrosis." (PMID 29619372, 2018). "In another injury model, mice transfected with an adenovirus vector containing the Cav-1 gene, demonstrated resolved lung fibrosis, observed by reduced fibrotic area in the lung relative to untreated mice." (PMID 28970796, 2017). "Wang’s group showed that the lung tissue of idiopathic pulmonary fibrosis patients also have reduced Cav-1 expression both at mRNA and protein levels compared to the lungs of healthy control subjects." (PMID 29250058, 2017). "Cav-1 is downregulated in several lung diseases such as asthma, chronic obstructive pulmonary disorder, and idiopathic pulmonary fibrosis." (PMID 27176222, 2016). "Studies in Cav1 knock out mice (Cav1−/−) showed that these mice exhibited extensive skin and lung fibrosis." (PMID 27077889, 2016). "The cav-1 null mice also develop pulmonary fibrosis, raising questions regarding the etiology of the PAH in this model which is yet to be clearly defined." (PMID 26106387, 2015). "There is decreased expression of cav-1 in lesional skin and lungs of patients with SSc and in lungs of patients with idiopathic pulmonary fibrosis (IPF)." (PMID 26106387, 2015).
pulmonary fibrosis (continued). "One protein intensively studied in context with pulmonary fibrosis and lung inflammation is caveolin-1 (Cav-1), which is abundantly expressed in lung epithelia, endothelia, and fibroblasts." (PMID 25635824, 2015). "When lung fibrosis is inhibited by restoring caveolin-1 activity using a caveolin-1 scaffolding domain peptide (CSD), a strong correlation is observed between fibrocyte number and fibrosis score." (PMID 24999331, 2014). "Experimental evidence also suggests that alterations of cav-1 function can be responsible for ECM production in fibroblasts and abnormal cav-1 function has been linked to lung fibrosis." (PMID 23580232, 2013). "During pulmonary fibrosis, it has been shown that Cav-1 expression is decreased in epithelial cells and fibroblasts compared with controls, but is increased in endothelial cells." (PMID 22040717, 2011). "Cav-1 serum levels are significantly increased in patients with explicit pulmonary fibrosis, as illustrated by the increased Cav-1 serum levels in patients with IPF in this study." (PMID 22040717, 2011). "Cav-1 expression was significantly decreased accompanied by overactive ER stress-mediated autophagy in particulate matter-induced pulmonary fibrosis model, while inhibition of ER stress could attenuate both autophagy and the reduction of Cav-1." (PMID 40012041, 2025). "In SSc‐ILD patients, Cav‐1 expression is diminished in leukocytes, particularly in PMNs and monocytes/macrophages, resulting in altered signaling pathways that drive the advancement of pulmonary fibrosis." (PMID 40778471, 2025). "This new finding shows that restoration of Cav1 in IKBM mice suggest a potential connection between NF-κB and Cav1 in lung fibrosis which is unknown but needs further investigation." (PMID 35083615, 2022). "Indeed, a Cav‐1‐derived peptide LTI‐03 entered phase 1 clinical trial with adaptation disease for idiopathic pulmonary fibrosis indication (NCT04233814)." (PMID 34889029, 2022). "Cav1-deficient (Cav1−/− or Cav1-KO) mice are viable and fertile, and abnormal brain vascular phenotypes have not been reported although Cav1-KO mice exhibited pulmonary fibrosis, hypertension, or cardiac hypertrophy as well as retinal vascular permeability." (PMID 33495460, 2021). "A similar mechanism involving miR-199a-5p and CAV1 has been proposed to exacerbate lung fibrosis." (PMID 34575957, 2021). "Overexpression of CAV1 can reduce infiltration of neutrophils and monocytes/macrophages and prevent bleomycin-induced pulmonary fibrosis, which may be related to its key regulatory role in inflammatory activities." (PMID 35069688, 2021). "Interestingly, our animal experiment showed that CAV1 mRNA expression increased when treadmill exercise was performed in mice with pulmonary fibrosis." (PMID 35069688, 2021). "Reduced expression of CAV1 will weaken the inhibitory effect of TGF-βR, thereby, activating the TGF-β signaling pathway, resulting in a large amount of extracellular matrix (ECM) generation, causing the occurrence of pulmonary fibrosis." (PMID 35069688, 2021). "Previous studies reported that some growth factors or proteins, like fibroblast growth factor-1 (FGF-1) or caveolin-1, could inhibit pulmonary fibrosis by regulating the degradation of TGF-βRI." (PMID 33808650, 2021). "Downregulation of Cav‐1 may be related to pulmonary fibrosis due to increased extracellular matrix production, hypercellularity, inflammation, and dysfunction of epithelial barrier." (PMID 32508059, 2020).